FOXO1 (forkhead box O1)
Diseases named in the same sentence as FOXO1 in open-access papers (continued):
Sharing a sentence is not in itself a finding about the gene and the disease.
colitis (10 papers, 2019 to 2026). Inflammation of the colon. "This defect can be attributed to aberrant IFNg expression in Foxo1-deficient Tregs since secondary deletion of IFNg rescues Treg-dependent colitis prevention." (PMID 33604081, 2021). "However, Foxo1-deficient Tregs are defective in preventing experimental colitis mediated by the transfer of conventional T cells into Rag-deficient mice." (PMID 33604081, 2021). "This study aimed to investigate the role of ENPP7 in dextran sulfate sodium (DSS)-induced colitis, with a particular focus on oxidative stress and FOXO1-related signaling pathways." (PMID 41981505, 2026). "CONCLUSIONS: ENPP7 attenuates DSS-induced colitis, at least in part, by modulating FOXO1-mediated antioxidant responses, thereby influencing oxidative stress and inflammatory processes." (PMID 41981505, 2026). "By downregulating FOXO1, miR-223 curtails M1 macrophage polarization, thereby reducing pro-inflammatory cytokine production and attenuating colitis." (PMID 40799643, 2025). "In our DSS-induced colitis model, FOXO1 expression was significantly reduced compared to wild-type (WT) mice, a finding consistent with prior studies linking elevated FOXO1 activity to exacerbated intestinal inflammation." (PMID 40799643, 2025). "We identify a novel dual-regulatory mechanism wherein miR-223 ameliorates colitis by shifting macrophage polarization from M1 to M2 via concurrent FOXO1 suppression and PPAR-γ activation." (PMID 40799643, 2025). "In the present study, we systematically investigate how miR-223 coordinates the PPAR-γ/FOXO1 signaling axis to reprogram macrophage phenotypes in DSS-induced colitis—an unexplored therapeutic nexus bridging epigenetic regulation and mucosal immunity." (PMID 40799643, 2025). "The identified PPAR-γ/FOXO1 signaling nexus not only clarifies colitis pathogenesis but also provides a druggable pathway for precision immunomodulation." (PMID 40799643, 2025). "An overexpression of miR-425 promotes Th17 cell production and IL-17A secretion by suppressing FOXO1 in colitis mice." (PMID 37834058, 2023). "Elp3 expression is downregulated by classical M1‐activating signals in myeloid cells, where it limits the production of pro‐inflammatory cytokines via FoxO1 phosphorylation, and attenuates experimental colitis in mice." (PMID 35920020, 2022). "In this study, FoxO1 transgenic mice (transgenic, FoxO1‐Tg) and C57BL/6 wild‐type (wild‐type, FoxO1‐WT) mice were used to establish chronic colitis by drinking water containing dextran sulphate sodium (DSS)." (PMID 32057181, 2020). "While this apparent contradiction (lower FOXO1 in a disease state) may reflect context-dependent roles of FOXO1 in inflammation, our data align with evidence that FOXO1 inhibition mitigates colitis severity." (PMID 40799643, 2025). "Foxo1-deficient Treg cells, which display a Th1-like phenotype, did not prevent disease in the T cell transfer colitis model." (PMID 30936873, 2019). "In DSS-induced colitis, colonic PPAR-γ expression decreased, while FOXO1 expression increased compared to WT controls." (PMID 40799643, 2025). "Building on our prior findings, we propose that miR-223 ameliorates colitis by coordinately regulating PPAR-γ and FOXO1 to reprogram macrophage polarization." (PMID 40799643, 2025). "By dual PPAR-γ/FOXO1 regulation, miR-223 shifted macrophages toward an anti-inflammatory M2 phenotype, attenuating colonic inflammation and tissue damage in DSS-induced colitis." (PMID 40799643, 2025). "Such mechanistic insight is pivotal given that optimal macrophage reprogramming requires simultaneous suppression of pro-inflammatory pathways (e.g., FOXO1) and activation of resolution signals (e.g., PPAR-γ)—a combinatorial regulatory paradigm unexplored in miRNA-mediated colitis therapy." (PMID 40799643, 2025). "In colitis mice, the expressions of SIRT1, FOXO1, FOXO3α, and FOXO4 could be increased by salidroside to attenuate inflammation reaction." (PMID 35479323, 2022).
ischemic stroke (10 papers, 2019 to 2025). A stroke disorder caused by obstruction of blood flow to the brain, due to thrombotic (local blood clot formation) or embolic (due to a blood clot or other material traveling from another site) event. "In a study of carotid atherosclerosis, a common cause of ischemic stroke, Mettl14 increased the m6A methylation of Foxo1 mRNA, which promoted Foxo1 translation and transcription factor activity to increase endothelial inflammation." (PMID 38360659, 2024). "The up-regulation of miR-139-5p in the preconditioned EVs was found to inhibit the anti-apoptotic effects of the FoxO1/Keap1/Nrf2 pathway, thereby potentially alleviating the impact of ischemic stroke." (PMID 40873771, 2025). "Gypenoside XLIX alleviates ischemic stroke injury by activating the PI3K/AKT/FOXO1 pathway, enhancing mitochondrial autophagy, and reducing oxidative stress, supporting its potential as a novel neuroprotective agent in stroke management." (PMID 40918528, 2025). "Tanshinone IIA alleviates ischemic–reperfusion injury via the miR-124-5p/FoxO1 axis, providing a new therapeutic target for ischemic stroke." (PMID 38549714, 2024). "miR-124-5p is the mature form of miR-124, indicating a potential link between miR-124-5p and FoxO1 in an ischemic stroke." (PMID 38549714, 2024). "FoxO1 has also been verified to be protective against ischemic strokes through the hippo signaling pathway, which controls organ size through regulation of cell proliferation, apoptosis and stem cell renewal." (PMID 35371601, 2022). "Calycosin-7-O-β-D-glucoside (CG), a representative drug, downregulated the expression of Bax, which further suggests that CG protects against ischemic stroke by activating the SIRT1/FOXO1/PGC-1α signaling pathway." (PMID 36105479, 2022). "In general, our findings expounded that Foxo1‐induced lessening miR‐92b boosted BBB damage after ischaemic stroke by raising NOX4 expression." (PMID 33955666, 2021). "In conclusion, the present study expounded that miR‐92b expression was lessened by Foxo1 after ischaemic stroke and that the lessening of miR‐92b facilitated the BBB damage by targeting NOX4." (PMID 33955666, 2021). "Additionally, magnolol causes a downregulation of Ac-FOXO1, induced by the SIRT1 expression, which means that magnolol can also exert a protective effect against ischemic stroke via resistance function against oxidative stress." (PMID 36105479, 2022). "To summarize, the activation of FoxO1 after ischemic stroke could increase hepatic gluconeogenesis and accelerate post-stroke hyper-glycemia, resulting in a high risk of mortality." (PMID 35371601, 2022). "During ischemic stroke, the reduced levels of p-FoxO1 may allow for increased FoxO1 translocation from the cytoplasm into the nucleus, thereby increasing the repression on the survivin promoter region and further contributing to cell apoptosis." (PMID 35371601, 2022). "Recent studies expounded that Foxo1 is also bound up with ischaemic stroke." (PMID 33955666, 2021). "Given this, we speculated that Foxo1 influenced the transcriptional expression of miR‐92b in ischaemic stroke." (PMID 33955666, 2021). "Taken together, these findings indicate that CG alleviates OGD/R-induced damage via the SIRT1/FOXO1/PGC-1α signaling pathway, and CG maybe a promising therapeutic candidate for brain injury associated with ischemic stroke." (PMID 31885537, 2019). "Besides, Foxo1 has been proven to be bound up with BBB damage after ischaemic stroke." (PMID 33955666, 2021). "This study aimed to explore the neuroprotective mechanisms of Gypenoside XLIX in ischemic stroke, focusing on the PI3K/AKT/FOXO1 signaling pathway." (PMID 40918528, 2025). "More momentously, Foxo1 is activated by phosphorylation in the ischaemic brains and has been confirmed to be bound up with the BBB dysfunction after ischaemic stroke." (PMID 33955666, 2021).
ischemic stroke (continued). "In conclusion, our results suggest that CG protects against ischemic stroke by activating SIRT1, which in turn upregulates FOXO1 and PGC-1α expression." (PMID 31885537, 2019). "Given the protective effects of CG on ischemic stroke, we hypothesized that CG protects against ischemic stroke via the SIRT1/FOXO1/PGC-1α signaling pathway." (PMID 31885537, 2019). "In the context of ischemic stroke, imbalanced mitophagy exacerbates neuronal injury, while the PI3K/AKT signaling pathway participates in mitophagy regulation by modulating downstream molecules such as the FOXO1 transcription factor to influence the expression of mitophagy-related genes." (PMID 40918528, 2025). "Besides, the limitation of this study was that there was no clinical application of Foxo1 in ischaemic stroke, and we would continue to probe into the clinical application value of Foxo1 and its specific inhibitors to further ameliorate this study." (PMID 33955666, 2021).
lupus (10 papers, 2010 to 2025). "In systemic lupus erythematosus (SLE) patients and lupus mice, M-MDSCs displayed reduced FoxO1 expression, and FoxO1 deficiency exacerbated B-cell dysfunction by activating the Met/COX2/PGE2 axis." (PMID 41562066, 2025). "Together, our data suggested that miR-183C acts through Foxo1 to regulate the production of inflammatory cytokine IFNγ, a key pathogenic cytokine in the lpr lupus model." (PMID 35873462, 2022). "In pristane-induced lupus mice with C-type lectin receptor Dectin3 deficiency, the expansion of LOX-1+ M-MDSCs via silencing FoxO1 induced the differentiation of Th17 cells and exacerbated the severity of lupus." (PMID 37733169, 2024). "The results of the transduction network of the differential expressed genes were analyzed by bioinformatics, combined with the GO and pathway analysis, which revealed that FoxO1 expressed in MDSCs of Dectin3−/− lupus mice lower than that in WT lupus mice." (PMID 34480018, 2021). "Notedly, the accumulation of M-MDSCs mainly decreased in Dectin3−/− lupus mice, and the nuclear transfer of FoxO1 negatively correlated with the expression of LOX-1 on M-MDSCs." (PMID 34480018, 2021). "The serum Anti-dsDNA and BUN were higher in Si-FoxO1 Dectin3−/− mice with lupus than in Si-NC-group mice." (PMID 34480018, 2021). "Dectin3 inhibited the nuclear metastasis of FoxO1 in lupus MDSCs through the Syk-Akt1 signal axis and participated in the development of lupus." (PMID 34480018, 2021). "The suppression of disease phenotype in lupus mice models was possible by the inhibitory peptide that acted via FoxO3 while FoxO1 level correlated with disease severity in several lupus patients." (PMID 34102081, 2021). "Our results indicated that Dectin3 negatively correlated with FoxO1 gene expression in MDSCs isolated from lupus mice." (PMID 34480018, 2021). "The results showed that percentages of MDSCs increased in BM, spleen, and kidney of Si-FoxO1 Dectin3−/− mice with lupus compared with Si-NC-group mice." (PMID 34480018, 2021). "In MDSCs of Dectin3−/− mice with lupus, the phosphorylation level of FoxO1 was significantly downregulated, and the level of nuclear metastasis of FoxO1 significantly increased." (PMID 34480018, 2021). "The expression of LOX-1 on M-MDSCs increased in BM, spleen, and kidney of Si-FoxO1 Dectin3−/− mice with lupus compared with Si-NC-group mice in vivo." (PMID 34480018, 2021). "The nuclear transfer of FoxO1 in Si-FoxO1 Dectin3−/− mice with lupus was lower than that in Si-NC-group mice." (PMID 34480018, 2021). "The percentage of apoptotic MDSCs decreased in Si-FoxO1 Dectin3−/− mice with lupus compared with Si-NC-group mice." (PMID 34480018, 2021). "The M-MDSCs in the spleens of different groups of mice with lupus were further sorted and enriched, revealing that the apoptosis level of M-MDSCs after knocking down FoxO1 significantly decreased, and the increase in the number of inflammatory Th17 cells was promoted in Dectin3−/− lupus mice." (PMID 34480018, 2021). "However, the splenomegaly in Si-FoxO1 Dectin3−/− mice with lupus was higher than in Si-NC-group mice." (PMID 34480018, 2021). "The symptoms of lupus nephritis were significantly aggravated in Si-FoxO1 Dectin3−/− mice with lupus compared with Si-NC-group mice, including decreased infiltration of crescentic and renal interstitial inflammatory cells and reduced amounts of glomeruli IgG deposits." (PMID 34480018, 2021). "In the present study, we aimed to investigate the effect of PNS on reversing SR in lupus mice and determine whether PNS reverses P-gp-mediated SR via SIRT1/FoxO1/MDR1 signalling in lymphocytes of lupus mice, which may be the major mechanism underlying the SR reversal potential of PNS in lupus." (PMID 35022006, 2022). "In addition, the nuclear transfer of FoxO1 increased in MDSCs of Dectin3−/− mice with lupus." (PMID 34480018, 2021). "PNS inhibited SIRT1/FOXO1/MDR1 signaling pathway in lymphocytes and reversed P-gp-mediated steroid resistance in lupus." (PMID 37483618, 2023).
lupus (continued). "The SIRT1/FoxO1/MDR1 signalling pathway has been confirmed in drug resistance of tumour cells, but there is little research on the field of SR in lupus." (PMID 35022006, 2022). "RT–PCR and Western blotting were used to detect the protein and mRNA expression levels of SIRT1, FoxO1, and MDR1 in SR splenic lymphocytes from lupus mice (SLCs/MPs)." (PMID 35022006, 2022). "Besides FOS, FOXO1, and FOXO3, upregulated TBK1 and TNFSF10 contributed to the activation prediction of ‘Systemic Lupus Erythematosus In B Cell Signaling’." (PMID 35406685, 2022). "The present study suggested that PNS reversed P-gp-mediated SR via the SIRT1/FoxO1/MDR1 signalling pathway, which might become a valuable drug for the treatment of SR in lupus." (PMID 35022006, 2022). "Si-FoxO1 RNA fragment (0.2 mL of 15 nmol) and 0.2 mL of negative control fragment were injected into Dectin3−/− mice with lupus intravenously (right)." (PMID 34480018, 2021). "Meanwhile, Si-FoxO1 RNA fragment (0.2 mL of 15 nmol) and 0.2 mL of negative control fragment were injected into Dectin3−/− mice with lupus intravenously (right)." (PMID 34480018, 2021).
muscle atrophy (10 papers, 2014 to 2025). The loss of muscle tissue due to inactivity or disease. "In denervation-induced muscle atrophy, activations of NF-κB and FoxO1 have a central role in muscle atrophy via upregulation of the expressions of MuRF1 and Atrogin-121,22." (PMID 36627369, 2023). "FOXO1 also activates the expression of atrophy-related genes such as Atrogin 1 and cathepsin L in various muscle atrophy-related conditions." (PMID 36386197, 2022). "In fact, MuRF1 and atrogin-1 are transcriptionally activated by FOXO1 and FOXO3 in skeletal muscle, and FOXO1 plays a pivotal role in the expressional regulations of MuRF1 and atrogin-1 in various muscle atrophy-related conditions." (PMID 25032690, 2014).
psoriasis (10 papers, 2017 to 2025). An autoimmune condition characterized by red, well-delineated plaques with silvery scales that are usually on the extensor surfaces and scalp. "Akt-induced phosphorylation and inactivation of the transcription factor FOXO1 is another mechanism underlying Treg dysfunction in psoriasis." (PMID 34501328, 2021). "The dysregulated Akt-Foxo1 pathway was described in Tregs in a murine model of psoriasis, and it is thought to be a critical factor contributing to the impaired function of these cells." (PMID 37892710, 2023). "The dysregulation of the Akt-FOXO1 pathway led to T cell dysfunction, which was also widespread in patients with psoriasis." (PMID 35265149, 2022). "Serum from patients with psoriasis induced the activation of Akt and phosphorylation and cytoplasmic translocation of FOXO1 in Tregs from healthy controls in vitro, although the Akt-inducing molecules in the serum were not identified." (PMID 34501328, 2021). "Together, the current findings provide the first suggestion of a new mechanism by which downregulation of miRNA-559 might induce proliferation in psoriasis through modulating PTEN/AKT/FOXO1 pathway by positive regulation of MTDH." (PMID 36348199, 2023). "Therefore, PI3K/AKT/FOXO cascade could contribute in the pathogenicity of psoriasis by downregulation and inactivation of FOXO1 which might lead to enhanced cell proliferation and keratinocyte hyperproliferation." (PMID 36348199, 2023). "Interestingly, Treg cells from psoriasis are defective in the Akt-FOXO1 signaling pathway." (PMID 32630692, 2020). "In this study, we identified NF-κB, FOXO1, CEBPB, STAT3, and ERK1/2 as the drug targets for the treatment of psoriasis." (PMID 37373186, 2023). "Circulating Tregs in patients with psoriasis expressed high levels of T-bet and IFN-γ mRNAs, showing a Th1-like phenotype in addition to enhanced phosphorylation of FOXO1 and Akt and cytoplasmic localization of FOXO1." (PMID 34501328, 2021). "While TNF-α induced the activation of FoxO1 in human fibroblasts, the TNF-α antagonist etanercept was reported to re-activate FoxO1 in patients suffering from psoriasis." (PMID 28098832, 2017). "Nevertheless, while mTOR fold increase did not correlate with FoxO1 in psoriasis patients, a significant correlation was found between mTOR and FoxO1 in AV patients." (PMID 38646331, 2024). "Comparing core signaling pathways of psoriasis and non-psoriasis and their downstream cellular dysfunctions, STAT3, CEBPB, NF-κB, and FOXO1 are identified as significant biomarkers of pathogenic mechanism and considered as drug targets for the therapeutic treatment of psoriasis." (PMID 37373186, 2023).